PCNA (proliferating cell nuclear antigen)
Diseases named in the same sentence as PCNA in open-access papers (continued):
Sharing a sentence is not in itself a finding about the gene and the disease.
Cirrhosis (9 papers, 2012 to 2025). A chronic disorder of the liver in which liver tissue becomes scarred and is partially replaced by regenerative nodules and fibrotic tissue resulting in loss of liver function. "Hepatocytes of liver tissues from the cirrhosis rats of Group 2 showed down-regulation of Bax staining with up-regulation of Bcl2-positive hepatocytes and more PCNA staining indicating severe damage with increased number of necrotic cells than their apoptosis." (PMID 23496995, 2013). "Considering the chromosomal instability characteristic in cirrhosis, it is possible that PCNA plays an important role in repairing the damaged DNA." (PMID 23056951, 2012). "It has been reported that PCNA express different isoforms in human HCCs compared to those in cirrhosis, suggesting that PCNA may play a role in HCC genesis." (PMID 23002138, 2012). "In preestablished cirrhosis, adenosine increases collagen degradation, prevents its accumulation, preserves the energy and functional states of the liver, increases DNA synthesis, the mitotic index, and the expression of proliferating cell nuclear antigen (PCNA)." (PMID 23056951, 2012). "In the current tissue evaluation, PCNA protein expression was noticeable at its highest in the hepatic tissues of TAA control rats, indicating an increasing rate of cirrhosis, cellular proliferation, and reduced tissue regenerations." (PMID 39723071, 2024).
medulloblastoma (9 papers, 2010 to 2024). A malignant, invasive embryonal neoplasm arising from the cerebellum. "Simultaneously, western blot results demonstrated that medulloblastoma cell associated proliferation antigen Ki67 and PCNA were significantly decreased after 20 μM BDDD-721 treatment for 24 h." (PMID 35802536, 2022). "IHC analysis identified islands of intense staining for the proliferation marker PCNA, surrounded by relatively quiescent areas in Pten deficient medulloblastomas." (PMID 20520772, 2010). "Further, the medulloblastoma related proliferation marker proteins of Ki67 and PCNA were detected in xenografts by western blot, and results showed more significantly reduced proteins of Ki67 and PCNA in BDDD-721 than that in curcumin-treated group." (PMID 35802536, 2022). "Co-immunohistochemistry/in situ hybridisation for the S-phase marker PCNA identified discrete “islands” of CD24+/PCNA+ cells in Ptch1 deleted medulloblastoma, while adult wild type cerebella were predominantly PCNA-/CD24-." (PMID 30657775, 2019). "Double-staining of tumor sections with an antibody against the proliferation marker PCNA and an anti-NeuN antibody revealed diffuse proliferation with scattered areas of staining for NeuN in SmoA1 +; Pten +/+ medulloblastomas." (PMID 20520772, 2010). "Bromodeoxyuridine (BrdU) labeling and proliferating cell nuclear antigen (PCNA) IHC (data not shown) showed that GADD34 mutation, either heterozygous or homozygous, did not significantly affect the number of proliferating cells in medulloblastoma in Ptch1+/− mice." (PMID 27802424, 2016).
myeloma (9 papers, 2008 to 2024). "The PCNA gene encodes a multifunctional protein which is essential for DNA replication and repair and is overexpressed in myeloma cells." (PMID 37048102, 2023). "As PCNA is a new and unexplored target for cancer treatment, we have here investigated the regulatory role of PCNA in 10 multiple myeloma (MM) cell lines using a multi-omics approach and a PCNA-targeting peptide, ATX-101, currently in clinical development." (PMID 39682151, 2024). "Following the results of this study, additional investigation is needed to compare NKp44-1 isoform expression by NK of MM patients to the levels of membrane PCNA expression by their myeloma cells and following myeloma treatment." (PMID 35563109, 2022). "In this study of multiple myeloma, we provided pre-clinical evidence that PCNA is expressed on the cell surface of MM cells and that incubation with mAb 14-25-9 enhances NK activity against MM cells." (PMID 35563109, 2022). "Serum BAFF levels have been shown to correlate with parameters of disease activity, such as bone marrow microvascular density and proliferating cell nuclear antigen expression, in patients with myeloma." (PMID 31658764, 2019). "For instance, targeting cytosolic PCNA in multiple myeloma cells using an APIM peptide has increased sensitivity to chemotherapy and induced apoptosis." (PMID 27759041, 2016). "Here we have designed a cell-penetrating APIM-containing peptide, ATX-101, that targets PCNA and show that it has anti-myeloma activity." (PMID 23936203, 2013). "PCNA inhibition induces apoptosis and sensitizes cells to melphalan, a common anti-myeloma drug." (PMID 37048102, 2023). "PCNA-targeting peptides were shown to inhibit the growth or to induce apoptosis in neuroblastoma, hormone-insensitive prostate cancer, triple-negative breast cancer, bladder cancer, and multiple myeloma." (PMID 29875773, 2018). "In the context of multiple myeloma, the expression of the HNRNPA2B1, USP1, RRM1, SPAG5, PCNA and TOP2A genes has been studied." (PMID 37048102, 2023). "Therefore, targeting PCNA by ATX-101 may be a novel strategy in multiple myeloma treatment." (PMID 23936203, 2013).
systemic lupus erythematosus (9 papers, 2012 to 2025). An autoimmune multi-organ disease typically associated with vasculopathy and autoantibody production. "Proliferating cell nuclear antigen (PCNA) was first discovered by Miyachi in 1978 in the serum of patients with systemic lupus erythematosus." (PMID 36992326, 2023). "The first observation of PCNA as an antigen in sera, isolated from patients with systemic lupus erythematosus, started a new field of research." (PMID 22309575, 2012). "Above all, ESWT is able to proliferate cells through the upregulation of early PCNA, which was originally thought to be a nuclear antigen in systemic lupus erythematosus (SLE) patients with autoimmune diseases." (PMID 35942112, 2022). "Proliferating cell nuclear antigen (PCNA), initially discovered in the serum of patients with systemic lupus erythematosus, has been found to exist as a homotrimer in various eukaryotic cells, forming a homotrimeric ring structure." (PMID 40357327, 2025). "The first eukaryote sliding clamp was identified in human cells as the “proliferating cell nuclear antigen” (PCNA), so-named for its identity as an antigen in proliferating cells in the sera of patients with systemic lupus erythematosus." (PMID 27148748, 2016). "Similar results where the ANA 12 PRI was positive but the conclusion of the lab was negative were found for SS-B, Ribosome P and PCNA where all 7, 1 and 10 discrepant samples, respectively, had lupus." (PMID 30161159, 2018).
thyroid cancer (9 papers, 1996 to 2025). "In clinical samples, overexpression of SphK1 correlated significantly with the expression of PCNA, suggesting a strong association between SphK1 overexpression and proliferation of thyroid cancer cells." (PMID 24970169, 2013). "An IHC analysis was performed to identify alterations in PCNA and cell apoptosis-associated protein (BAX) levels in thyroid cancer tissues." (PMID 39459033, 2024). "The results verified that GPX4 knockdown obviously inhibited protein expression of Ki-67 and PCNA, as well as proliferation in thyroid cancer cells." (PMID 36626251, 2023). "The present study showed that overexpression of miR-195-5p inhibits TERT, which significantly reduces the presence of Ki67 and PCNA in thyroid cancer cells CAL-62, and inhibits the proliferation of CAL-62." (PMID 34482792, 2021). "Furthermore, the expression of SphK1 correlated significantly with the expression of proliferating cell nuclear antigen (PCNA), indicating that proliferation of thyroid cancer cells is associated with the expression of SphK1." (PMID 24970169, 2013).
triple-negative breast carcinoma (9 papers, 2017 to 2025). An invasive breast carcinoma which is negative for expression of estrogen receptor (ER), progesterone receptor (PR), and human epidermal growth factor receptor 2 (HER2). "This peptide mimics a critical sequence in the cancer-associated PCNA isoform (caPCNA), blocking PCNA chromatin and DNA polymerase δ binding, leading to cytotoxicity in triple-negative breast cancer cells." (PMID 41170373, 2025). "TAT-based Y211F cell-penetrating PCNA peptide (CPPP) has been reported to be effective in suppressing the proliferation of TNBC (triple negative breast cancer) cells that have become treatment resistant, especially to EGFR TKI." (PMID 33498235, 2021). "In triple-negative breast cancer patients, Tyrosine 211 (Y211) PCNA phosphorylation is known to be related to cancer proliferation and a lowered survival rate." (PMID 33498235, 2021). "Consistent with this view, downregulation of endogenous PCNA in pancreas, prostate, breast and brain tumor cell lines by a siRNA approach and the blockade of NKp44-PCNA interaction in triple negative breast cancer cells by a monoclonal antibody increased NK cytotoxicity and tumor killing." (PMID 38504978, 2024). "When PCNA was knocked down within monocyte derived macrophages and then infected with HSV1716 in the presence of triple negative breast cancer (TNBC) cells, it was found that the presence of PCNA is required for HSV replication." (PMID 39205238, 2024). "We examined associations of CCL2, CCR2, phospho-SMAD3 and phospho-p42/44MAPK with molecular subtype including: luminal A and B, HER2+ and triple negative breast cancers, which were identified using clinical guidelines on ER, PR, HER2 and Ki67/PCNA expression." (PMID 33888841, 2021). "Consistent with our observations in the triple-negative breast cancer cells, guides targeting Rosa26 exhibited minimal dropout over five passages, while guides targeting RPA3 or PCNA were depleted up to 90-fold." (PMID 28337968, 2017). "In particular Monensin demonstrated to reduce triple-negative breast cancer (TNBC) development without displaying anti-proliferative effect on malignant tissues, evident by no significant changes in Proliferating Cell Nuclear Antigen (PCNA) and Ki-67 expression." (PMID 40969947, 2025).
ameloblastoma (8 papers, 2008 to 2025). The most common odontogenic tumor, arising from the epithelial component of the embryonic tooth and usually affecting the molar-ramus region of the mandible or maxilla. "The present study included a large series of ameloblastic tumors, comprising 161 ameloblastomas and four ACs, to determine the PCNA and Ki-67 positivity of each ameloblastoma variant." (PMID 23229269, 2013). "The results of the research data analysis revealed that the highest expression of KI-67 and PCNA was found in the follicular and mixed ameloblastoma subtypes (follicular-plexiform) compared to the plexiform subtype." (PMID 40373818, 2025). "As a result, with a limited number of samples, this shows that the expression of Ki-67 and PCNA in the follicular and mixed type ameloblastoma (follicular-plexiform) is higher than in plexiform subtype ameloblastoma." (PMID 40373818, 2025). "The level of Ki-67 and PCNA expression can help pathologists differentiate between subtypes of ameloblastoma and assess their potential behavior." (PMID 40373818, 2025). "We have found that Ki67 and PCNA-expressing cells are present in the DLRs, but they are significantly fewer than in ameloblastoma." (PMID 31685919, 2019). "The proliferative potential of the DLRs and Ameloblastoma was assessed by expression of Ki67 and PCNA." (PMID 31685919, 2019). "In contrast, when we used the PCNA antibody, only one significant difference was found: the AC displayed a proliferation index that was relatively higher than one ameloblastoma (DA, p<0.05)." (PMID 23229269, 2013). "When differences between the immunopositivity for PCNA and Ki-67 were compared, the percentages were higher for PCNA in all types of ameloblastomas and ameloblastic carcinomas." (PMID 23229269, 2013). "In the present study, dental follicle, dentigerous cyst, unicystic ameloblastoma and ameloblastoma were evaluated in terms of Ki-67 and PCNA expression levels to justify the recurrence and different clinical behaviors." (PMID 24551787, 2013). "In the literature, there are some studies that have used both PCNA and Ki-67 as markers of cell proliferation in ameloblastomas." (PMID 23229269, 2013). "When analyzing cell proliferation with PCNA, we found significant differences only between the ameloblastic carcinomas (93.3%) and the desmoplastic ameloblastomas (p<0.05)." (PMID 23229269, 2013). "It has been reported the detected PCNA expression level in 23 cases of ameloblastoma, indicating that PCNA Index of follicle formation type (34.56%±14.00%) is of higher significance than plexiform type (24.44%±15.74%)." (PMID 18366613, 2008). "Some studies suggest that PCNA expression levels may be increased in more aggressive ameloblastoma cases." (PMID 40373818, 2025). "PCNA expression was located in tumor epithelial cells from each ameloblastoma sample." (PMID 40373818, 2025). "Hence, the present study aimed to investigate the expression of Ki-67 and PCNA in dental follicle, dentigerous cyst, unicystic ameloblastoma and ameloblastoma using immuno-histochemistry method." (PMID 24551787, 2013). "Key words:Ameloblastomas, ameloblastic carcinoma, PCNA, Ki-67, cell proliferation markers." (PMID 23229269, 2013). "In addition, these previous studies have also shown a similiar trend in the KCOTs and ameloblastoma that had higher proliferation indices of Ki-67 and PCNA than in other kinds of odontogenic cysts including the DC and RC." (PMID 22778705, 2012). "By employing PCNA staining, epithelial lining of OKC has been demonstrated to have a comparable proliferative potential to that of ameloblastoma." (PMID 29508125, 2018).
asthma (8 papers, 2013 to 2023). "This layer was composed of α-smooth muscle actin- and PCNA-positive cells in vehicle-treated asthma lung tissues." (PMID 36755351, 2023). "Patients with severe asthma were confirmed to present increased levels of α-SMA and PCNA, associated with higher mortality." (PMID 35721212, 2022). "Nicotine upregulates cyclinD1 expression in HBSMCs in smokers with asthma and also promotes hASM proliferation by increasing the expression of two proliferative markers, known as cyclinE and proliferating cell nuclear antigen (PCNA)." (PMID 34069141, 2021). "Whereas SMI could inhibit the increase of PCNA expression induced by asthma (P < 0.01)." (PMID 24010863, 2013). "The expression of PCNA and absorbance of MTT assay in asthma rat ASMC was also significantly increased." (PMID 24010863, 2013). "Furthermore, western blot analysis further confirmed that BIBF1000 treatment attenuated the lung expression of α-SMA, PCNA, iNOS, MMP-2, MMP-9, and COX-2, compared to vehicle-treated asthma lung tissues." (PMID 36755351, 2023). "Our results also showed that the expressions of PCNA and α-SMA were increased in the lung tissues of mice asthma models and the hyperproliferative ASMCs, while QFXBF could alleviate the overexpression of α-SMA and PCNA." (PMID 35186095, 2022).
brain tumor (8 papers, 2002 to 2024). "Next to this, PCNA staining was also uniformly detected in the brain tumor whereas the surrounding brain remained quiescent, with the exception of actively cycling cells in the subventricular zone." (PMID 27739525, 2016). "Moderate DR significantly reduced microvessel density, increased the apoptotic index, but had little effect on the PCNA labelling index in the CT-2A brain tumour." (PMID 12085212, 2002). "Additionally, PCNA positive tumor cells could be detected in a brain tumor and within the optic nerve of the injected side, but not in the optic nerve of a wild-type eye." (PMID 27739525, 2016). "Brain tumor tissue sections were stained for H&E, DAPI (nuclear staining), protein 14-3-3γ (TNT marker), PCNA (proliferation marker), and GFAP (a glial marker) and analyzed by confocal microscopy with subsequent 3D reconstruction." (PMID 34267246, 2021). "By considering another profile, the highest expression in proliferating cell nuclear antigen (PCNA) and cyclin D2, and the lowest expression in cyclin E were observable in all types of brain tumors." (PMID 31565199, 2019). "To further examine proliferation characteristics of the retinoblastoma and brain neoplasms of rb1cr1/rbl1cr1 MDKO tadpoles, we performed PCNA immunohistochemistry." (PMID 27739525, 2016).
colon adenocarcinoma (8 papers, 2005 to 2023). "We also investigated the correlation between Gpx-2 protein expression and clinicopathological factors in patients with colon adenocarcinoma, e.g., a correlation between Gpx-2 expression and proliferating cell nuclear antigen (PCNA) expression." (PMID 37834097, 2023). "PCNA-labeling indices of colonic adenocarcinomas in mice treated with 100- and 400-ppm nelumal A were markedly less than those of the AOM/DSS-treated group." (PMID 33436792, 2021). "PCNA seems to be a new marker to study human colonic cell proliferation, and high PCNA expression has prognostic significance in colon adenocarcinoma." (PMID 34595111, 2021). "PCNA-labeling index of colonic adenocarcinomas developed in groups 2, 3, and 4 was significantly smaller than group 1 (P < 0.001)." (PMID 15892897, 2005). "PCNA and apoptosis indices and scores of β-catenin, COX-2, iNOS and nitrotyrosine expression in colonic adenocarcinomas." (PMID 15892897, 2005). "In WiDr human colon adenocarcinoma cells, Fx may induce cell cycle arrest during the G0/G1 phase and apoptosis through inhibition of Rb phosphorylation and increased the expression of a CDK and proliferating cell nuclear antigen (PCNA) inhibitory protein, p21WAF1/Cip1." (PMID 26264004, 2015).
gastric ulcer (8 papers, 2010 to 2023). An ulcerated lesion in the mucosal surface of the stomach. "Increased expression of PCNA in the stomach occurred in samples of indomethacin-induced gastric ulcerations, while its expression declined markedly in the EGb 761 pre-treated and treated groups." (PMID 36080365, 2022). "The gastric tissues obtained in the ethanol-induced gastric ulcer rat model were used for immunohistochemical localization of PCNA antibody." (PMID 29513129, 2018). "As a result, the increase in the number of PCNA positive cells showed that okra has a healing effect on ethanol-induced-gastric ulcer model." (PMID 29513129, 2018). "The gastric tissues obtained in the acetic acid-induced gastric ulcer model were used for immunohistochemical localization of PCNA antibody." (PMID 24454726, 2014). "The present study was designed to investigate whether Cissus quandrangularis extract (CQE) had healing effects on gastric ulcer, through modulation of polyamines and proliferating cell nuclear antigen (PCNA) in rats." (PMID 20931084, 2010). "The mild to moderate immunoreactivity to PCNA on EGb761 administration could be explained by EGb 761’s capacity to regenerate damaged tissues and normalise the proliferative process following re-epithelialization, differentiation, and effectiveness in healing gastric ulcers." (PMID 36080365, 2022). "Gastric tissues obtained from acetic acid-induced gastric ulcers were used for immunohistochemical analysis of HSP-70, p-AKT, and PCNA." (PMID 29849711, 2018). "The healing ability was evaluated using the acetic acid-induced gastric ulcer model and histological and immunohistochemical analysis (HE, PAS and PCNA)." (PMID 24454726, 2014). "Dehydrocostus lactone could relieve ethanol-induced gastric ulcers in mice, which was considered to be related to the decrease in TNF-α, COX-2, and MDA and the increase in IL-10 and PCNA." (PMID 37109624, 2023). "Gastric ulcers generated in the stomachs of rats by piroxicam administration demonstrated the degeneration of surface mucous cells as well as intense immunoreactivity to COX-2 and PCNA." (PMID 36080365, 2022).